GLYATL1B (glycine-N-acyltransferase like 1B)
Description:
Putative acyltransferase which transfers an acyl group to the N-terminus of glutamine. Can use phenylacetyl-CoA as an acyl donor.
Synonyms: GLYATL1P3
Gene: Protein-coding gene on chromosome 11 (59,086,307 to 59,094,786, forward strand). Ensembl gene ENSG00000255151.
Subcellular location (Human Protein Atlas): Golgi apparatus; Cytosol
Gene Ontology:
Molecular function: glutamine N-acyltransferase activity; glycine N-acyltransferase activity
Biological process: glutamine metabolic process
Cellular component: mitochondrion
Homologues: Orthologues: chimpanzee GLYATL1B (95% identical), macaque GLYATL1B (79% identical), tropical clawed frog glyatl2 (32% identical), zebrafish si:dkey-76k16.6 (26% identical), zebrafish si:ch73-106k19.2 (24% identical), Caenorhabditis elegans T10B10.4 (21% identical), zebrafish si:dkey-76k16.5 (20% identical), Caenorhabditis elegans ZK185.3 (17% identical), Caenorhabditis elegans F43H9.4 (13% identical). Paralogues in human: GLYATL1 (82% identical), GLYATL2 (47% identical), GLYAT (39% identical), GLYATL3 (32% identical).